EGF (epidermal growth factor)
Diseases named in the same sentence as EGF in open-access papers (continued):
Sharing a sentence is not in itself a finding about the gene and the disease.
glioblastoma (continued). "It was discovered that glioblastoma progression is actively influenced by a few soluble proteins generated from microglia, including transforming growth factor-β (TGF-β), epidermal growth factor (EGF), and stress-inducible protein 1 (STI 1)." (PMID 40727443, 2025). "Thus, investigating the effects of STLs on PMT induced by various glioblastoma severity-related factors (e.g., TGF-β, EGF, hypoxia, etc.)remains an extremely important research goal for future work." (PMID 39857717, 2025). "Key members of the gene network,including vascular endothelial growth factor A (VEGFA),epidermal growth factor (EGF), and the catalytic subunitA of phosphatidylinositol-4,5-bisphosphate-3-kinase(PIK3CA), have been identified as important genetic markersof glioblastoma involved in angiogenesis." (PMID 39944803, 2024). "Many years of our research on glioblastoma biology indicate that EGF is not able to prevent GB cell senescence in vitro." (PMID 36292985, 2022). "Primary EGFRvIII positive (and SOX2 (SRY-Box Transcription Factor 2) positive or SOX2 negative) glioblastoma cells differentially responded to EGF and TGFβ." (PMID 36292985, 2022). "Microglia release epidermal growth factor (EGF), which also stimulates glioblastoma cell invasion." (PMID 35600367, 2022). "Furthermore, EGCG has been reported to inhibit epidermal growth factor (EGF)-induced activation of the EGF-receptor (EGFR), a frequently encountered aberrant oncogenic pathway in glioblastoma and many other cancers." (PMID 31139406, 2019). "EGF signals through the mitogen-activated protein kinase/extracellular signal-regulated kinase (MAPK/ERK) pathway, as well as the phosphatidylinositol 3-kinase (PI3K) pathway in glioblastoma cells and other cell lines." (PMID 31698752, 2019). "In the U251 and U87 glioblastoma cell lines, p-EGFRTyr1068 is spontaneously expressed, while EGF-induced p-EGFRTyr1173 is persistent (no less than 48 h)." (PMID 29152086, 2017). "This alanine residue is perfectly conserved within the Furin-like domain among other epidermal growth factor genes and appears mutated also in ERBB2 and ERBB4, although not in glioblastoma." (PMID 26860319, 2016). "A number of reports indicated paracrine secretion as paramount to glioblastoma growth, with ligands such as TGFα, IL-6, ΙL-8, HGF and heparin binding EGF playing central role, further supporting the hypothesis." (PMID 27004406, 2016). "We now show that the cardiac glycoside ouabain, an inhibitor of Na,K-ATPase, inhibits EGFR signaling in medulloblastoma cells, but not glioblastoma cells, and prevents EGF-induced cell migration, a prerequisite for an invasive phenotype." (PMID 25052069, 2014). "In U87 glioblastoma cells, ouabain did not inhibit EGF-induced Erk1/2 or Akt activation and, surprisingly, further increased EGF-induced EGFR phosphorylation." (PMID 25052069, 2014). "Our finding that RhoG contributes to Rac1 activation downstream of EGFR in glioblastoma cells however, contrasts to published observations that EGF-stimulated Rac1 activation is independent of RhoG in HeLa cells." (PMID 22966858, 2012). "We also observed that RhoG is activated by both HGF and EGF, two factors that are thought to be clinically relevant drivers of glioblastoma invasive behavior, and that RhoG is overexpressed in human glioblastoma tumors versus non-neoplastic brain." (PMID 22966858, 2012). "Additionally, excessive expression of growth factors, such as EGF, PDGF, and VEGF, in the glioblastoma microenvironment stimulates receptor tyrosine kinases and activates downstream signaling pathways, including PI3K-AKT-mTOR, promoting glioblastoma cell survival and proliferation." (PMID 37834408, 2023). "The molecular effects of Luteolin were also investigated in relation to the epidermal growth factor (EGF)-induced proliferation of glioblastoma cells and the ability of Luteolin to induce apoptosis in these cells, as EGFR was found to be overexpressed in glioblastomas." (PMID 36992138, 2023).
glioblastoma (continued). "Because we showed a decrease in the migration capacity of glioblastoma cells under treatment with miR‐218 in our studies, we could conclude then that these changes might be the result of the impact of miR‐218 on CDC42, STAT3, EGF and CTTN." (PMID 35702951, 2022). "The increase in CIC protein expression in our cell systems following EGF/FGF treatment was unexpected and thus were further validated in glioblastoma (GBM) cell lines and primary brain tumor-initiating cells (BTIC)." (PMID 33115448, 2020). "Therefore, while under normoxic conditions, EGF stimulates the activation of both the PI3K and the MAPK pathways and the induction of VEGF, in glioblastoma cells, hypoxic conditions lead to the suppression of the PI3K/RhoA/C pathway and an exclusive switch to the MAPK pathway." (PMID 31698752, 2019). "We analyzed the differential expression of potential target genes in a glioblastoma cell line in two nested RNAi experimental conditions and one negative control, contrasting expression with EGF stimulation against expression without EGF stimulation." (PMID 31438847, 2019). "Notably, targets of these miRNAs might be involved in glioblastoma signaling (PI3K signaling pathway), STAT3 Pathway, TGF-β, ERK5, Rho Family GTPases, PTEN, ERK/MAPK, and EGF pathways." (PMID 29455644, 2018). "Our studies show that the cardiac glycoside and specific inhibitor of Na,K-ATPase, ouabain, can inhibit EGF-induced signaling and cell migration in medulloblastoma cells, but not glioblastoma cells, and indeed support the notion of developing novel therapeutic approaches targeting the sodium pump." (PMID 25052069, 2014). "There is a general agreement that EGF functioning is increased in GBM (glioblastoma multiform),but it is not yet clear whether this is due to over-activity of the receptor (EGFR), or to increasedlevels of the ligand." (PMID 23637756, 2013). "In previous unpublished studies, we attempted an in-depth characterization of the microRNA expression profiles of glioblastoma (GB) specimens, primary cell lines derived from GB growing as neurospheres (GB-NS) in the presence of b-fibroblast growth factor (b-FGF) and epidermal growth factor (EGF)." (PMID 22869051, 2012). "In the cell death pathway, EGF treatment induces apoptosis via AKT1 inhibition in EGFR overexpressed dominant-negative Ras mutant cell lines, or via phosphorylation of STAT3 in glioblastoma; however, the mechanisms for these pathways are not clear." (PMID 38789573, 2024). "To investigate the degree to which the expression levels of these genes respond to EGF in another glioblastoma cell line, we perform triplicated qPCR experiments in the glioblastoma cell line LNZ308 with and without EGF treatment." (PMID 31438847, 2019). "Unlike the ATP-competitive TKIs, PTUPB treatment does not deplete EGF-induced phosphorylation of EGFR (p-EGFRTyr1173) until 6 h post dose, while Gefitinib, a widely-used EGFR TKI, inhibits EGF-induced p-EGFR in early phase (30 min) in glioblastoma cells." (PMID 29152086, 2017).
colon carcinoma (149 papers, 1999 to 2025). "It was determined that the regulation of CAIII, which has been determined to be associated with cancer, decreases in colon cancer cells under the influence of the EGF cytokine." (PMID 39590368, 2024). "SPINK1 possesses structural similarities to EGF, and is associated with inflammatory states and various cancers, such as chronic pancreatitis, inflammatory bowel disease and colon cancer." (PMID 33015026, 2020). "We previously demonstrated that non-toxic doses of Celecoxib induced the immediate phosphorylation of Erk1-2 in colon tumor associated fibroblasts (TAFs), increasing their responsiveness to epidermal growth factor (EGF)." (PMID 25987127, 2015). "Our results provide a mechanism linking EGF and HO-1, and they support the development of therapeutic strategies to reduce colon cancer progression caused by EGF." (PMID 25122478, 2014). "Epidermal growth factor (EGF)-induced proliferation of colon cancer cells plays an important role in colon cancer progression and is mediated by loss of tumor suppressor FOXO3 activity." (PMID 21639915, 2011). "Proliferation of EGF treated colon cancer cells is mediated by loss of FOXO3 activity, and here we showed this pathway to be inhibited by genistein." (PMID 21639915, 2011). "The effect of genistein on proliferation stimulated by EGF-mediated loss of FOXO3 was examined in human colonic cancer HT-29 cells." (PMID 21639915, 2011). "Colon cancer-associated MS4A12 is a novel colon-specific component of store-operated Ca2+ (SOC) entry sensitizing cells for epidermal growth factor (EGF)-mediated effects on proliferation and chemotaxis." (PMID 19781065, 2009). "Dysregulations in the EGF signaling pathway have been associated with colon cancer." (PMID 39590368, 2024). "Through M2-polarization of tumor-associated macrophages, EGF secreted by colon cancer cells enhances the cancer-driving effect of the tumor microenvironment, then promoting immuno-suppression, angiogenesis and neovascularization, as well as stromal activation and remodeling." (PMID 37853459, 2023). "However, as polyp size is an important determinant of subsequent risk for malignant change in human colon cancer, further studies are warranted of the effects of EGF." (PMID 25389045, 2015). "For example, fluorescence dye-labeled annexin V was given into colon tumor-bearing mice after one week of cetuximab treatment and showed a peak accumulation at 24 h after intravenous administration, which was associated with a decrease of epidermal growth factor uptake and activation of caspase-3." (PMID 24949860, 2014). "Epidermal growth factor can induce CD55 expression in colon cancer cells through the p42/44 MAPK pathway." (PMID 40596619, 2025). "Nanoparticles with EGF had a more pronounced tumour suppression of the SW260 colon cancer cell line and also induced apoptosis in more colon cancer cells." (PMID 40650240, 2025). "Upon administering EGF to SLC5A1 knockdown colon cancer cells, the EGFR phosphorylation level was restored." (PMID 39781340, 2025). "For example, in colon cancer cells, increased epidermal growth factor (EGF) signalling resulted in increased β-catenin acetylation, which was reduced in the presence of HDAC6 inhibition." (PMID 39941046, 2025). "Subsequently, we performed single-molecule imaging of oncogenic KRAS mutants between 2 and 5 min after EGF stimulation in SW48 colon cancer cells that had undergone 1 h of serum starvation." (PMID 40949096, 2025). "In colon cancer, EGF secreted by colon cancer cells promotes the polarization of TAMs into M2 TAMs by binding to the EGF receptor (EGFR) on TAMs, which in turn activates the AKT signaling pathway." (PMID 39889181, 2025). "Epidermal growth factor (EGF) promotes the accumulation of claudin-3 in the human colon cancer HT-29 cell line." (PMID 40723233, 2025).
colon carcinoma (continued). "In the same way, MAT2A expression in human colon cancer resections, mice polyps and cell lines were increased, correlating with epidermal growth factor (EGF), insulin-like growth factor (IGF)-I and leptin-induced proliferation." (PMID 39941901, 2025). "We suggest that the CAIII gene is promising as a targeted therapy due to the decrease in EGF-effected CAIII gene regulation in colon carcinoma." (PMID 39590368, 2024). "In conclusion, in colon cancer cells, EGF contributes to the carcinogenesis process by reducing mRNA and protein CAIII expression, which plays a role in cell proliferation, angiogenesis, and apoptosis mechanisms." (PMID 39590368, 2024). "The aim of the present study was to determine the effect of EGF cytokines on CAIII regulation in colon cancer cell lines." (PMID 39590368, 2024). "Genistein, a phytoestrogen, mediates a cancer promotor EGF protein, which inhibits the proliferation of HT-29 colon cancer cells." (PMID 38898481, 2024). "They reported that, when EGF was used in colon cancer cell lines, glycosyltransferase, including FUT3, FUT6, and ST3GAL1/3/4, was elevated." (PMID 38528852, 2024). "Their results revealed that epidermal growth factor which was secreted by colon cancer cells play contributory role in M2 polarization of macrophages through activation of PI3K/AKT pathway and secretion of cytokines." (PMID 36776333, 2023). "Despite accumulating evidence suggests that the EGFR or transforming growth factor α (TGFα)/ EGFR signaling pathways play a critical role in colon cancer progression, the EGF autocrine loop in colon cancer is still poorly investigated." (PMID 37853459, 2023). "In colon carcinoma cells, calcitriol reduced EGFR expression and augmented SPRY expression, encoding a physiological antagonist to the EGF-triggered cascade." (PMID 36364774, 2022). "EGF has also been described to induce EMT in different model systems like colon cancer and mesothelioma cell lines, and was reported to cooperate with TGFβ for EMT induction." (PMID 33777943, 2021). "In colon cancer cells undergoing EGF/bFGF-induced EMT, FUT2, one of the two fucosyltransferases which synthesize the H antigen was down-regulated, suggesting its EMT-preventing role." (PMID 34356834, 2021). "Whilst the promoting effect of EGF on PD-L1 surface expression for colon cancer cells, seems to manifest in T3M4 cells, this mechanism is partially or even not involved in BxPc3 and A818-6 cells, respectively." (PMID 34202040, 2021). "In colon cancer cells, genistein reduces epidermal growth factor- (EGF-) stimulated proliferation, though favoring nuclear maintenance of FOXO3 (active state) and dephosphorylation." (PMID 34336089, 2021). "Recently, it was reported that insulin and EGF synergize in activating PD-L1 expression in colon cancer cells, an effect that involves the enhanced transport of PD-L1 to the cell surface." (PMID 34202040, 2021). "A nonlinear ANN was employed in this study to uncover important aspects of biological cue-signal-response systems using TNF-, EGF-, and insulin-mediated response of HT-29 human colon carcinoma cells." (PMID 32314080, 2020). "CCK-8 assay results indicated that free 5Fu, PLGA@5Fu NPs, PLGA@5Fu/PFC NPs and EGF-PLGA@5Fu/PFC NPs inhibited the proliferation of colon cancer cells in a concentration-dependent manner." (PMID 32345258, 2020). "AQP3 is expressed in colon cancer, and both epidermal growth factor (EGF) and oestrogen, which are known to be involved in the occurrence of cancer, are considered upstream regulators of AQP3 expression." (PMID 32662230, 2020). "EGF is a commonly used binding agent for EGF receptor-overexpressing solid tumors including colon cancer." (PMID 32345258, 2020). "Human SW620 colon cancer cells were chosen as model EGF receptor overexpressing tumor cells in this study to investigate the targeting ability of EGF-PLGA@5Fu/PFC NPs." (PMID 32345258, 2020).
colon carcinoma (continued). "In the present study, we elucidated novel angiogenesis-independent crosstalk between the VEGF and the EGF pathways in colon cancer cells." (PMID 31717527, 2019). "In this study, we found angiogenesis-independent novel crosstalk between the VEGF and the EGF pathways in the regulation of colon cancer cell proliferation." (PMID 31717527, 2019). "The EGFRs are overexpressed in colon cancer cells and its activation through epidermal growth factor (EGF) is responsible for the proliferation, survival, and metastasis of cells." (PMID 30781696, 2019). "More interestingly, the most recent study reported that MIIP interacts with PP1 and serves as its substrate of dephosphorylation at S303, which undergoes phosphorylation by PKCε upon EGF-treatment in colon cancer." (PMID 31092266, 2019). "In support of this notion, the claudin-2 promoter was affected in the opposite direction by EGF in Caco2 colon cancer and in MDCK tubular epithelial cells." (PMID 31726679, 2019). "In colon cancer cells, autocrine EGF signaling is a well-known critical pathway that activates proliferation." (PMID 31717527, 2019). "Many sporadic colon cancers contain activating mutations in the GTPase K-RAS, EGF (epidermal growth factor), and VEGF (vascular endothelial growth factor), which enhance canonical WNT signaling by increasing the concentration of β-catenin in the nucleus." (PMID 31623618, 2019). "Accordingly, silencing claudin-2 in the colon cancer cell line Caco-2 and in tubular cells prevented EGF- and TNFα-induced increase in cell proliferation." (PMID 31726679, 2019). "Integrin β1 is recycled by trafficking and shed from colon cancer cells in response to EGF stimulation in a Rab25-dependent manner." (PMID 29515334, 2018). "ERRα positively regulated the cell proliferation, migration and invasion of colon cancer cells, and the suppression of ERRα completely reduced the EGF treatment-induced proliferation of colon cancer cells." (PMID 30185207, 2018). "This interaction between ERRα and EGFR suggests a potential novel function of ERRα in the EGF-mediated survival and proliferation of colon cancer cells." (PMID 30185207, 2018). "Integrin β1 is shed from colon cancer cells in response to EGF stimulation in a Rab25-dependent manner." (PMID 29515334, 2018). "There have been almost no reports of ILD occurring among patients taking Cetuximab (a neutralising monoclonal epidermal growth factor antibody) to treat colon cancer." (PMID 30458863, 2018). "Colon cancer cells were exposed to EGF for three-time intervals and then pretreated with the membrane-impermeable chemical cross-linker BS3 allowing resolution of dimeric components of EGFR." (PMID 29499765, 2018). "Nevertheless, further studies on the respective effects of EGF, integrin β1, and Rab25 in the progression and metastasis of colon cancer would enable the therapeutic application of these drugs." (PMID 29515334, 2018). "Because both EGF/EGFR pathway activation and integrin β1 have been associated with colon cancer progression, the present study aimed to investigate changes in integrin β1 expression and trafficking in response to EGF stimulation." (PMID 29515334, 2018). "Further investigation showed that trametinib partially restrained the up-regulation of ERRα induced by the EGF treatment, and ERRα inhibition increased the sensitivity of colon cancer cells to trametinib." (PMID 30185207, 2018). "In HT-29 colon cancer cell lines deprived of epidermal growth factor (EGF), it was seen that EGFR is mainly located at in Ld domains but upon activation with EGF or TGFα, EGFR translocates to Lo domains, to produce its downstream signaling." (PMID 30518103, 2018). "In this report, we showed that the suppression of ERRα completely reduced the EGF treatment- induced cell proliferation and survival in colon cancer cells." (PMID 30185207, 2018).